AFP (alpha fetoprotein)
Diseases named in the same sentence as AFP in open-access papers (continued):
Sharing a sentence is not in itself a finding about the gene and the disease.
Cirrhosis (1,030 papers, 1995 to 2026). A chronic disorder of the liver in which liver tissue becomes scarred and is partially replaced by regenerative nodules and fibrotic tissue resulting in loss of liver function. "Both plasma and urine TGF-β1 levels are higher in patients with HCC than in those with cirrhosis, display comparable diagnostic ability as AFP to discriminate HCC from cirrhosis." (PMID 40269686, 2025). "This aligns with the current study’s findings, which show that elevated AFP levels in the blood are linked with larger tumor size, higher rates of spreading of malignancy, and more advanced cirrhosis." (PMID 40429981, 2025). "In the scoring system, the following were emphasized as risk factors: AFP ≥400 ng/ml, tumor diameter ≥5 cm, total bilirubin ≥17,1 μmol/L, aspartate aminotransferase ≥40 U/L, albumin level <35 g/L, and presence of cirrhosis." (PMID 40709064, 2025). ", who reported that in HCV patients with cirrhosis, AFP level ≥ 6 ng/mL was associated with the development of HCC in multivariate analysis." (PMID 39753619, 2025). "In contrast, tumor-associated proteins such as AFP, although secreted during tumor progression, can also be elevated in non-malignant inflammatory liver conditions, including hepatitis and cirrhosis, and are subject to metabolic clearance by the liver." (PMID 41002319, 2025). "In the univariate analysis, factors such as advanced age, male sex, low platelet count, presence of cirrhosis, and elevated AFP levels showed a significant association with the development of HCC (all with P<0.05)." (PMID 41379183, 2025). "The diversity in patient populations, tumor biology (e.g., MVI and AFP levels), underlying liver conditions (e.g., cirrhosis vs. non-cirrhosis), and surgical approaches (AR vs. NAR) limits the ability to draw uniform conclusions." (PMID 40507240, 2025). "The results suggest that these biomarkers, especially platelet count, AFP, and PT, should be carefully considered in clinical practice for cirrhosis risk stratification." (PMID 40384539, 2025). "Significant risk factors independently associated with HCC included age over 45 years, presence of cirrhosis, longer infection duration, elevated AFP levels, and comorbidities." (PMID 40662001, 2025). "Among these, circ_0009910 demonstrated the highest diagnostic accuracy, significantly outperforming AFP and showing robust associations with tumor size, stage, metastasis, and cirrhosis severity." (PMID 40429981, 2025). "In this study, patient characteristics indicated that individuals with a history of cirrhosis and higher levels of AFP had a greater risk of MVI (odds ratio 4.27; 95% CI, 1.20-9.78; P < .05), which is consistent with previous studies." (PMID 38870535, 2024). "While imaging remains the cornerstone of HCC detection, biomarkers like AFP add diagnostic value, especially in cases where imaging results are inconclusive or in high-risk patients such as those with chronic hepatitis B or cirrhosis." (PMID 39682122, 2024). "At the same time, HCC related to MAFLD was associated with lower prevalence of cirrhosis, alpha-fetoprotein concentration > 400 ng/mL, tumor size > 5 cm, multinodular tumors, advanced tumors, or microvascular invasion than HCC of other etiologies." (PMID 38693556, 2024). "A higher POLR2J4 level was closely associated with the presence of cirrhosis (P = .029), higher AFP (P < .001), advanced Edmondson grade (P = .034), TNM stage (P = .031), and the presence of vascular invasion (P = .022) in HBV–HCC patients." (PMID 39412398, 2024). "Current guidelines recommend monitoring of high risk groups (e.g. primarily those with cirrhosis) with regular ultrasound scanning and alpha-fetoprotein (AFP) levels, which is the only biomarker approved for surveillance." (PMID 38809396, 2024).
Cirrhosis (continued). "It is noteworthy that increased levels of serum AFP are also associated with other clinical conditions such as hepatitis, liver failure or cirrhosis, ICC, gastric cancer, germ cell tumors, and inflammatory bowel ataxia telangiectasia." (PMID 39064538, 2024). "EASL and DGVS guidelines for HBV and HCC recommend HCC screening by abdominal ultrasound every six months with the optional determination of alpha-fetoprotein in chronic HBV patients with enhanced HCC risk (patients with advanced fibrosis or cirrhosis)." (PMID 38673017, 2024). "All three guidelines recommend biannual US surveillance, with some advocating for the addition of AFP testing to enhance early detection in high-risk populations such as those with cirrhosis." (PMID 39682122, 2024). "Given the high risk of HCC in patients with cirrhosis, particularly those with a history of chronic alcohol use, routine surveillance with imaging and serum alpha-fetoprotein (AFP) levels is recommended for early detection." (PMID 39310412, 2024). "Further analysis by logistic regression showed that serum AFP was independently associated with significant fibrosis, advanced fibrosis, and cirrhosis." (PMID 37241155, 2023). "Factors associated with time-to-PLC were baseline alpha-fetoprotein >10 ng/mL (HR: 4.01, 95% CI, 1.85–8.71), platelet count ≤150 (HR: 4.90, 95% CI, 1.95–12.28), and Child-Pugh B cirrhosis (vs. Child-Pugh A: HR: 2.54, 95% CI, 1.27–5.08)." (PMID 36881615, 2023). "Factors associated with time-to-PLC in multivariable analysis were AFP >10 ng/mL (HR: 4.01, 95% CI, 1.85–8.71), platelet count ≤150 (HR: 4.90, 95% CI, 1.95–12.28), and Child-Pugh B cirrhosis (vs. Child-Pugh A: HR: 2.54, 95% CI, 1.27–5.08)." (PMID 36881615, 2023). "The poorer differentiation, larger tumor size, positive of AFP, and cirrhosis were associated with a poorer prognosis." (PMID 36717904, 2023). "LncRNA expression in HCC patient EVs is significantly higher than in chronic hepatitis/cirrhosis or healthy controls, offering better diagnostic ability than AFP for early-stage HCC." (PMID 37809326, 2023). "Their expression levels in EVs of HCC patients were significantly higher than those of chronic hepatitis/cirrhosis or healthy controls, presenting a potent diagnostic ability, and even better than AFP in diagnosing early-stage HCC." (PMID 37006626, 2023). "Before PSM (102 laparoscopic vs. 40 robotic cases), compared to laparoscopic AR, robotic AR was significantly associated with a lower rate of cirrhosis, smaller tumor number and size, a lower AFP level, and a higher rate of repeat hepatectomy setting." (PMID 37190148, 2023). "Univariate analysis revealed that the risk factors for OS included cirrhosis, AFP, total bilirubin, Child–Pugh score, tumor number, tumor size, satellite nodules, and tumor invasion status (all p < 0.05)." (PMID 37909228, 2023). "The results showed that ANKFN1 expression was positively associated with cirrhosis (P = 0.005) and serum alpha-fetoprotein (AFP) levels (P = 0.045)." (PMID 35725908, 2022). "National screening using liver sonography and alpha-fetoprotein is strongly recommended for established high-risk groups (hepatitis virus carriers or cirrhosis patients) (strongly recommended)." (PMID 36142000, 2022). "After surgical treatment, all recurrence risk models incorporate markers of tumor biology (e.g. AFP, vascular invasion, tumor size/number) with cirrhosis an additional powerful marker of recurrence after resection." (PMID 35142988, 2022). "One study reported that serum AFP predicted the risk of HCC in Caucasian patients with HBV-monoinfection with compensated cirrhosis on long-term tenofovir or entecavir therapy." (PMID 36421714, 2022). "In patients with cirrhosis or an increased level of AFP, which are both known risk factors for HCC, MWA also demonstrated better DFS than RFA." (PMID 35053997, 2022).
Cirrhosis (continued). "In univariable Cox analyses, FAR, NLR, MLR, PLR and SII were significantly related to OS, as well as age, male sex, ascites, AFP, cirrhosis, tumor size, macrovascular invasion, BCLC stage, blood loss, blood transfusion and major hepatectomy." (PMID 35606690, 2022). "There were positive correlations between risk score and AFP level, cirrhosis, tumor size, and tumor stage in the GSE14520 cohort." (PMID 35693827, 2022). "The upregulation of ANKFN1 in HCC was associated with cirrhosis, alpha-fetoprotein (AFP) levels and poor prognosis." (PMID 35725908, 2022). "8, the FIB-4 index, platelet count, cirrhosis status, age, and AFP were associated with HCC development during entecavir treatment in univariate analyses." (PMID 34996935, 2022). "In South Korea, it is currently recommended to perform a liver ultrasound and serum alpha-fetoprotein testing at 6-month intervals for high-risk groups (hepatitis B and C virus carriers, cirrhosis)." (PMID 36142000, 2022). "In subgroup analysis of patients with vascular invasion, cirrhosis, and HBsAg positive or AFP positive, MALAT1 overexpression was significantly associated with shorter PFS and OS." (PMID 36685103, 2022). "Common parameters of these four risk models such as age, cirrhosis or platelet count and AFP are documented risk factors for HCC." (PMID 36291847, 2022). "In regard to clinicopathological factors evaluated other than invasion, there was not a significant association between FOXO3 overexpression and AFP levels, cirrhosis, gender, HBV infection, metastasis, TNM staging, tumor nodularity or tumor size." (PMID 34771514, 2021). "Meanwhile, LTBP1 alone is also remarkably overexpressed in HCC patients and can show a better diagnostic performance in distinguishing HCC from HVB or cirrhosis as compared to AFP especially in the early staged disease." (PMID 33562077, 2021). "This panel has a higher diagnostic performance than AFP in distinguishing HCC from high-risk cirrhosis populations, with the area under the receiver-operating characteristic curve (ROC) of 0.807 for the panel versus 0.650 for AFP in the validation set." (PMID 33869206, 2021). "Three factors, namely, the presence of cirrhosis, AFP levels, and haemoglobin levels are related to underlying liver function, and clinical T stage is associated with the tumour status." (PMID 34126955, 2021). "Approximately 30% of patients with HCC have AFP levels below 20 ng/mL, and 10% to 42% of AFP abnormalities are caused by pregnancy, gonadal embryoma, active hepatitis, the active inflammatory stage of cirrhosis, or metastatic liver tumors." (PMID 34277397, 2021). "Currently, patients with cirrhosis or at high-risk of HCC are recommended to take the test of AFP and US every 6 months." (PMID 33297335, 2020). "What is more, in the subgroup analysis including only studies that used cirrhosis patients as a control population, AFP+AFP-L3%+DCP also showed a good diagnostic performance, with the pooled sensitivity and specificity of 0.81 and 0.82, respectively." (PMID 33015170, 2020). "OPN is also markedly increased in the plasma of HCC patients and emerged as a diagnostic biomarker that improves AFP performance in HCC surveillance among patients with HBV or HCV-related cirrhosis." (PMID 32576292, 2020). "In univariate analysis, female gender, habitus of alcohol drinking and smoking, presence of cirrhosis or ascites, Child-Pugh class B liver function, and lower platelet count were significantly associated with the AFP group." (PMID 32845895, 2020). "Australian guidelines recommend screening with 6 monthly ultrasound and alpha fetoprotein in all people with cirrhosis and in high risk populations that include Aboriginal and Torres Strait Islander people over the age of 50." (PMID 32881958, 2020). "Eight potential risk factors (sex, age, comorbidities, cirrhosis, AFP, tumor size, location abutting major vessels, and AM) for LTP were examined through univariate and multivariate analyses." (PMID 33102233, 2020).
Cirrhosis (continued). "Surprisingly, HBV infection was also associated with 7-year earlier onset, more cirrhosis, higher AFP, more MVI, and lower PLR and Child–Pugh score in ICC." (PMID 31179237, 2019). "Most HCC are found to be in livers with a background of cirrhosis or hepatitis in China and are associated with relatively high AFP levels." (PMID 31171030, 2019). "The first incorporates routinely measured laboratory tests for evaluating the underlying liver disease of patients with cirrhosis and the rate of change in AFP in a six-month risk prediction model." (PMID 29301497, 2018). "In dataset GSE14520, the univariate Cox analyses showed that tumor size, nodular number (multiple vs. single), cirrhosis, AFP level, BCLC stage, CLIP stage and TNM stage were associated with the OS of the patients." (PMID 28434945, 2017). "In conclusion, sAxl shows high diagnostic accuracy at early stage HCC as well as cirrhosis, thereby outperforming AFP." (PMID 28526812, 2017). "All patients where cirrhotic, with the most frequent cause of cirrhosis being chronic alcoholism in 41% of cases, while 85% (n = 23) of the patients were Child-Pugh score A. The median initial alpha-fetoprotein (AFP) level was 5 ng/mL." (PMID 28441447, 2017). "In contrast, AFP remained a good diagnostic marker for HCC patients regardless the background of cirrhosis." (PMID 28157705, 2017). "Several studies have shown that age, sex, cirrhosis and AFP levels are predictors for long-term HCC risk in CHB." (PMID 29290966, 2017). "Univariate analysis showed that older age, cirrhosis, diabetes mellitus, lower platelet counts, genotype 1, more prolonged prothrombin time and higher AFP level were risk factors of HCC development." (PMID 26968010, 2016). "Univariate analysis showed that Child-Pugh grade, tumor size and number, serum total bilirubin and AFP concentrations, tumor thromboses, and cirrhosis were significantly associated with OS." (PMID 27387757, 2016). "In Model 1, which included age, sex, and baseline status of known risk factors, only cirrhosis and AFP were significantly and independently associated with CHC progression." (PMID 27478498, 2016). "In distinguishing HCV or HBV-associated HCC from cirrhosis, AFP continued to have superior diagnostic performance compared to the novel biomarkers." (PMID 27219517, 2016). "Previous studies reported that the prevalence of increased serum AFP varies from 10% to 43% in adult patients with CHC and suggested an association between an increased serum AFP and advanced fibrosis or cirrhosis." (PMID 26640716, 2015). "Child-Pugh B cirrhosis (P = 0.024) and a high level of serum alpha-fetoprotein (P = 0.039) were independent risk factors for poor overall survival." (PMID 25885683, 2015). "High K7 expression was significantly associated with cirrhosis (P = 0.035), lower serum AFP level (P = 0.026) and poorly histological grade (P = 0.048)." (PMID 26311117, 2015). "In the diagnostic setting of HCC on cirrhosis, all these miRNAs appeared to perform better than AFP, which, in our series, displayed an AUC of 0.73 (CI: 0.62–0.85)." (PMID 26509672, 2015). "If a patient has known risk factors for HCC, such as the presence of cirrhosis, increasing levels of AFP have been shown to correlate with the development of HCC." (PMID 22655201, 2012). "Firstly, HBV or HCV infection and exacerbation of underlying liver disease determine fluctuating levels of AFP in patients with cirrhosis." (PMID 22792474, 2012). "Secondly, and even more disheartening for those with known cirrhosis, the diagnostic performance of AFP for HCC detection is inadequate as it is only elevated in 40-60% of positive cases." (PMID 19656391, 2009).
Cirrhosis (continued). "Patients with chronic hepatitis and/or cirrhosis therefore form a high risk population which would benefit from regular screening for HCC by serial measurement of serum alpha-fetoprotein (AFP) levels and hepatic ultrasound." (PMID 19578489, 2008). "AGP has diagnostic significance for HCC and cirrhosis, in which the combined use of alpha-fetoprotein (AFP) and AGP assays may be useful for early diagnosis of HCC patients with cirrhosis presenting." (PMID 40278409, 2025). "HCC surveillance is recommended every six months in high-risk patients—such as those with cirrhosis of any etiology or chronic HBV infection—using ultrasound in combination with alpha-fetoprotein (AFP), which increases sensitivity for early detection from 45% to 63%." (PMID 41012682, 2025). "Recognizing this limitation, we developed alternative, highly accurate diagnostic models: notably, the miR-200a-3p/AFP combination achieves an AUC > 0.9 for differentiating HCC from CHB/cirrhosis, fulfilling the need for precise HCC detection in high-risk cirrhotic patients." (PMID 41459517, 2025). "High-risk population screening: Patients with hepatitis, cirrhosis, and populations in high-incidence areas of liver cancer should regularly monitor alpha-fetoprotein (AFP), abnormal prothrombin (PIVKA-II), and abdominal ultrasound to achieve early diagnosis and treatment." (PMID 41426604, 2025). "Univariate analysis showed that significant factors associated with HCC after DAA were: history of treated HCC, cirrhosis, evidence of portal hypertension, higher AFP at the start or end of DAA therapy, higher bilirubin, lower platelets, lower albumin, and older age." (PMID 38273255, 2024). "Other benign causes of AFP elevation include viral hepatitis, cirrhosis, and liver trauma." (PMID 39685906, 2024). "It is often associated with hepatitis B or cirrhosis and shows elevated AFP levels." (PMID 39120829, 2024). "However, the sensitivity and specificity of AFP alone are insufficient for it to serve as a standalone diagnostic tool, as elevated AFP can also be observed in patients with other liver conditions such as chronic hepatitis and cirrhosis." (PMID 39682122, 2024). "Furthermore, 1-MNAM demonstrated superior capability in distinguishing HCC from the high-risk population (cirrhosis) compared to traditional blood markers (such as AFP, CA19-9, and CA125)." (PMID 38890166, 2024). "In this study, we screened ten potential risk factors for PHLF through a univariable logistic regression analysis; these included cirrhosis, intraoperative blood loss, intraoperative blood transfusion, extent of liver resection, inflow occlusion, operating time, lactate ratio, PT, AFP, and TBil." (PMID 38512494, 2024). "For patients with high-risk factors for HCC, including cirrhosis from any cause, chronic hepatitis B infection, or hereditary hemochromatosis, experts may recommend screening with alpha-fetoprotein (AFP) and liver ultrasound." (PMID 37240623, 2023). "However, this association between AFP levels and cirrhosis was mentioned in another study in which it was proposed as a biomarker for the liver fibrosis stage." (PMID 38138039, 2023). "Furthermore, serum AFP was found to be independently associated with significant fibrosis, advanced fibrosis, and cirrhosis." (PMID 37241155, 2023). "Clinical correlation analyses revealed that a higher risk score was associated with death, cirrhosis, vascular invasion, main tumor size >5 cm, AFP >300 ng/ml, poorly differentiated histology grade (G3‐4), and advanced stage (TNM stage III‐IV, BCLC phase B‐C, and CLIP scoring ≥2)." (PMID 35651292, 2023). "High-risk population: single tumor diameter > 5 cm or 2–3 tumor nodules, the maximum tumor diameter ≤ 3 cm (BCLC A/CNLC Ib), with any of the following risk factors: 1 hepatic cirrhosis; 2 accompanied by ≥ 1 of the following serological changes: AFP 200–400 ng/mL, AFP-L3 5–10% and DCP 100–400 mAU/mL." (PMID 37369911, 2023).